GSDME (gasdermin E)
Diseases named in the same sentence as GSDME in open-access papers (continued):
Sharing a sentence is not in itself a finding about the gene and the disease.
cancer (continued). "GSDME is considered as a potential tumor suppressor gene in several types of cancers, such as gastric and hepatocellular carcinomas Recently, it has also been demonstrated to mediate pyroptosis via its activated N-terminus (GSDME-N) domain that is specifically cleaved by caspase-3 and granzyme B." (PMID 35972780, 2022). "As a vital player in cancers, it is urgent to explore the crucial epigenetic mechanism of GSDME." (PMID 35462927, 2022). "Upregulated GSDME by reversal of epigenetic silencing and facilitated the occurrence of pyroptosis was considered as an important pyroptosis-based cancer chemotherapy strategy, but we suggest more attention should be paid to the oncogenic role of GSMDE when being upregulated." (PMID 35164740, 2022). "In addition to activating the NLRP3 inflammasome to induce cancer cell pyroptosis, ROS can also induce pyroptosis through the caspase-3/GSDME pathway." (PMID 36612023, 2022). "whereas, GSDMB and GSDME were moderately expressed in pan-cancer." (PMID 35922531, 2022). "However, several recent studies have shown that TNF or chemotherapeutic drugs induce pyroptosis through caspase-3 cleavage of GSDME protein in GSDME-positive cancer cells or normal cells." (PMID 35896522, 2022). "High expressions of GSDME and PJVK were associated with subtype C5, indicating these two genes might mainly play a cancer suppressor role." (PMID 35164740, 2022). "Notably, GSDME expression is higher in normal tissues such as the gastrointestinal tract and kidney than in cancer tissues." (PMID 35819638, 2022). "It is suggestive that specific induction of pyroptosis in cancer cells by activating GSDME may provide an effective approach to enhance antitumor immunity." (PMID 36387211, 2022). "Among them, GSDME is specifically cleaved by caspase-3 in its linker, resulting in a GSDME-N fragment that penetrates the membrane and induces pyroptosis, providing new insights into cancer chemotherapy." (PMID 36189207, 2022). "The AMP-activated protein kinase (AMPK) pathway was activated in response to energy stress and could trigger caspase-3/GSDME-mediated pyroptosis in cancer." (PMID 36387211, 2022). "Different expression levels of GSDME determine whether cancer cells tend to apoptosis or pyroptosis during chemotherapy." (PMID 36091247, 2022). "Elevated GSDME activity exerts suppressive effects on carcinogenesis and cancer progression." (PMID 36003332, 2022). "Among gasdermins, GSDME was a potent executor that could be cleaved by the apoptotic caspase-3 and induce robust pyroptosis in different types of cancer cells." (PMID 35756622, 2022). "The gasdermin family is closely related to the process of cell death, and a previous study conducted by Shao and colleagues showed that overexpression of GSDME resulted in increase of sensitivity to chemotherapeutic agents, including cisplatin, in cancer cells." (PMID 35289335, 2022). "Among them, GSDME has been widely investigated for its involvement in pyroptosis of cancer cells." (PMID 35002520, 2022). "In fact, GSDME is expressed in many normal tissues but is silenced in most cancer cells." (PMID 36189310, 2022). "In addition to caspase-3, killer cell or CAR T cell -derived GZMB also cleave GSDME at D270, unleashing its pore-forming activity to trigger caspase-independent pyroptosis in GSDME-positive cancer cells." (PMID 33941231, 2021). "GSDME suppression in cancer cells is most dependent on the DNA methylation of the GSDME promoter." (PMID 34459122, 2021). "Moreover, the caspase inhibitor or depletion of GSDME blocked chemotherapeutic drug-induced pyroptosis in cancer cells." (PMID 33634141, 2021). "Indeed, GSDME expression in cancer cells was upregulated after treatment with the DNA methyltransferase inhibitor 5-Aza-2’-deoxycytidine (decitabine)." (PMID 33406603, 2021).
cancer (continued). "However, the direct activation of GSDME by granzyme B implies that CTLs and NK cells are capable of inducing pyroptosis in GSDME-expressing cancer cells even when apoptosis signaling pathways are impaired in the targets." (PMID 33406603, 2021). "In addition, recent studies showed that chemotherapeutic or molecular targeted agents-induced activation of caspase-3 triggers pyroptosis by cleaving GSDME specifically, resulting in a decrease of cell growth in various cancer cells." (PMID 33558527, 2021). "The function of GSDME in cancer has been increasingly prominent as the investigations has advanced." (PMID 34381728, 2021). "Moreover, GSDME-positive cancer cells reportedly undergo pyroptosis, while GSDME-negative cancer cells undergo apoptosis upon stimulation with chemotherapy drugs." (PMID 33589596, 2021). "The GSDME could be cleaved by activated caspase 1 and caspase 3, and then trigger the transition of cancer cells from apoptosis to pyroptosis." (PMID 34421915, 2021). "Some results indicate that cisplatin and Val-boroPro (Talabostat) induce pyroptosis in cancer cells suggesting that they may provide additional advantages in the treatment of cancers with high levels of GSDME expression." (PMID 33602906, 2021). "Moreover, the promoter region of GSDME gene was mostly hypomethylated or partially methylated in cancer cell lines and primary tumors." (PMID 34901025, 2021). "Therefore, we are only just beginning to understand the molecular mechanisms of GSDME and its emerging role in cancer research, a great deal of work requires to be done to further broad the applications of GSDME in human cancers." (PMID 34381728, 2021). "Some researchers propose that GSDME may be a promising biomarker for cancer detection, for predicting the 5-year patient survival rate 83, and for use in GSDME-mediated PCD initiated immunogenic cell death (ICD) in GSDME-overexpressing cells." (PMID 34335940, 2021). "Collectively, the combination of GSDME activators and chemotherapeutics might be effective approaches for controlling human cancers." (PMID 33634141, 2021). "However, various chemotherapeutic agents have recently been shown to mediate the cleavage of GSDME by inducing caspase-3 activation, leading to the pyroptosis of cancer cells." (PMID 34931767, 2021). "The cleavage of GSDMD and GSDME in cancer cells could be induced by various therapeutic strategies, including chemotherapy drugs, molecular target therapies, or immune cell therapy." (PMID 34421915, 2021). "Third, GSDME expression was found to be associated with cancer immunity and clinical survival prognosis; however, we were not sure that GSDME influenced clinical survival via definite signal pathway." (PMID 34381728, 2021). "The transition highly relies on the expression level of GSDME in cancer cells." (PMID 34421915, 2021). "Moreover, nonclassical or secondary pyroptosis induced by caspase 3 cleavage of GSDME has been observed in cancer cells treated with chemotherapy drugs such as lobaplatin and navitoclax." (PMID 35004674, 2021). "While the excessive activation of inflammasome-induced pyroptosis in cancer treatment, such as in CAR-T therapy, could also cause serious consequences; The CAR-T cells elicited GSDME–mediated cancer cell pyroptosis and released pyroptosis-related factors." (PMID 34421915, 2021). "The mode of cancer cell death (apoptosis or pyroptosis) depended on the expression level of GSDME." (PMID 33634141, 2021). "For instance, Gasdermin E (GSDME) is turning out to be a critical GSDM in cancer cells." (PMID 34795266, 2021). "Silencing GSDME attenuates the cytotoxicity of TPL against cancer cells." (PMID 34108030, 2021). "GSDME expression is silenced in most cancer cells but expressed in many normal tissues." (PMID 33033617, 2020).
cancer (continued). "From this, studies confirmed that in cancer tissues with low GSDME expression, the DNA methyltransferase inhibitor Decitabine can inhibit the hypermethylation of the GSDME promoter and increase the expression of GSDME, then promoting the occurrence of pyroptosis." (PMID 33133646, 2020). "The anti-cancer drugs induced GSDME cleavage was further investigated in these cells." (PMID 32332857, 2020). "This implied that the activation of caspase-3/GSDME-dependent pyroptosis might be an alternative therapeutic strategy for cancer treatment." (PMID 32149134, 2020). "Of note, GSDME is silenced in most cancers but expressed in normal tissue." (PMID 33179413, 2020). "In short, these studies imply that GSDME is a new potential contributor to cancer cell death." (PMID 32341339, 2020). "GSDME has a gasdermin-N domain capable of inducing pyroptosis in GSDME-expressing cancer cells." (PMID 31637008, 2019). "However, further research is warranted to support the clinical utility of GSDME-targeted therapeutics in cancer patients." (PMID 31492049, 2019). "In addition, because of the important role of GSDMD/GSDME in the regulation of both pyroptosis and cancer therapy sensitivity, the study which focus on GSDMD/GSDME and cancer treatment sensitivity will assign a new role for pyroptosis in the future." (PMID 31616642, 2019). "In addition, reduced GSDME expression decreases sensitivity of cancer cell lines to etoposide-induced apoptosis, while its ectopic overexpression increases their sensitivity." (PMID 30976076, 2019). "Whether GSDME-dependent pyroptosis contributes to anti-cancer effects of chemotherapy is determined." (PMID 30804337, 2019). "The GSDME-mediated pyroptosis could be activated by chemotherapy-induced caspase-3 activation in cancer cells." (PMID 31616642, 2019). "These very recent findings changed the view on the expected role of GSDME in cancer." (PMID 31434357, 2019). "Moreover, a GSDME was recently shown to be specifically cleaved by caspase-3 and induce pyroptosis in certain GSDME-expressing cancer cells." (PMID 30283066, 2019). "Therefore, GSDME is the target for the synergistic anti‐cancer effects of HMB." (PMID 39950759, 2025). "However, GSDME is often silenced in most cancer cells and expressed in many normal tissues." (PMID 38987821, 2024). "However, in some cancer cells, the promoter region of GSDME is in a state of low expression owing to abnormal hypermethylation, and caspase-3 activated by anticancer drugs cleaves the downstream apoptotic protein poly (ADP-ribose) polymerase (PARP) instead of GSDME, thereby initiating apoptosis." (PMID 39526199, 2024). "Therefore, targeting GSDME is a promising strategy for the treatment of cancer." (PMID 38169676, 2024). "In addition, transfection of exogenous GSDME into cancer cell lines with no or low GSDME expression reduced the proliferation and survival of cancer cells, whereas silencing of the GSDME gene significantly enhanced the cloning and invasion capabilities of cancer cells." (PMID 39526199, 2024). "Indeed, utilizing the TCGA database, we validated the expression of GSDME across various cancers and found GSDME to be significantly down-regulated in bladder, breast, cervical, colon, renal clear cell, ovarian, prostate, endometrial, and uterine sarcoma cancers." (PMID 40630838, 2024). "However, due to hypermethylation of the GSDME gene, most cancer cells lack caspase-3-derived GSDME." (PMID 39062587, 2024). "However, we limited the effect of GSDME-mediated pyroptosis on cancer therapy." (PMID 37686375, 2023). "Some chemotherapeutic agents, such as DDP, 5-FU, and carboplatin, have been demonstrated to combat cancer drug resistance by inducing GSDME-dependent pyroptosis, while whether natural compounds can also suppress drug resistance through this pathway needs further investigation." (PMID 38239395, 2023). "Targeting GSDME-mediated pyroptosis may improve the chemotherapy sensitivity of cancer cells." (PMID 36867605, 2023).
cancer (continued). "Therefore, DNA methyltransferase inhibitors such as decitabine may sensitize cancer cells to pyroptosis by re-establishing gasdermin E (GSDME) expression." (PMID 36831197, 2023). "However, apoptosis occurs in cancer cells with low GSDME levels." (PMID 36523974, 2022). "Therefore, it is reasonable to screen small molecules that could upregulate the expression levels of DFNA5/GSDME to induce pyroptosis, for cancer treatments." (PMID 36611966, 2022). "Additionally, involvement of caspase-3-GSDME-N axis in this process implicated by mechanistical analysis further suggests that dioscin could induce pyroptosis via cleavage of GSDME and formation of GSDME pore on the cancer cell membrane." (PMID 36209102, 2022). "In addition to inhibiting cancer cell proliferation, GSDME promotes immune cell infiltration." (PMID 36091247, 2022). "However, the role of GSDME and its related proteins in cancer requires further research." (PMID 34553845, 2022). "However, caspase-3 tends to induce apoptosis in cancer cells with low GSDME expression." (PMID 36091247, 2022). "As a consequence of the discovery, the passive effects of chemotherapy were exacerbated by GSDME-induced pyroptosis, the role of GSDME in normal tissue destruction has been gradually realized, which implies a bright prospect of GSDME as a therapeutic target for diseases, not limited to cancers." (PMID 35462927, 2022). "Thus, GSDME was potential to be a novel target for cancer prevention and treatment." (PMID 34335940, 2021). "Thus, treatment with DNA methyltransferase inhibitors, such as decitabine, may restore GSDME expression, thereby sensitizing cancer cells to pyroptosis." (PMID 33406603, 2021). "Since the silencing of the GSDME gene makes it difficult to induce cancer cell pyrotosis with apoptosis-inducing drugs, and since reduced expression levels of GSDME are associated with poor prognosis in cancer patients, the promoter methylation may be a potential drug target in cancer therapy." (PMID 33406603, 2021). "Interestingly, the basal level of GSDME protein was positively correlated with the sensitivity to CAP in three selected cancer cell lines, implying GSDME might be a potential biomarker of prognosis in the forthcoming cancer CAP treatment." (PMID 32341339, 2020). "Moreover, GSDME was frequently epigenetically silenced in different cancer types." (PMID 31434357, 2019). "Therefore, the activation of caspase-3/GSDME-dependent pyroptosis might be an alternative therapeutic strategy for cancer treatment." (PMID 31492049, 2019). "This study shows that GSDME-dependent pyroptosis is novel mechanism for the eradication of colon cancer cells by lobaplatin, which may be of great significance for the clinical application of anti-cancer therapeutics." (PMID 31616642, 2019). "However, more research is needed to further unravel the exact function of GSDME in cancer." (PMID 31434357, 2019). "Caspase-3 is one of the key proteins in the cell pyroptotic pathway, and the activation of it elicits the upregulation of the tumor suppressor gene gasdermin E (GSDME) and activates the pyroptosis switch in cancer cells." (PMID 40006592, 2025). "USP48 binds to gasdermin E (GSDME) and deubiquitinates the K48 junction at the K120 and K189 sites to stabilize GSDME, which sensitizes cancer cells to focal death and improves the response to immunotherapy." (PMID 40083330, 2025). "Recent research in 2017 revealed that GSDME can convert caspase-3-mediated apoptosis induced by TNF or chemotherapy drugs to pyroptosis, providing new insights into cancer chemotherapy." (PMID 38987821, 2024). "Therefore, the role of GSDME-mediated pyroptosis may be cancer-type-specific." (PMID 39526199, 2024). "They found that cancer cells had increased levels of PKM2, gasdermin E N-terminal domain (GSDME-N) and cleaved-caspase-3." (PMID 39398428, 2024).
cancer (continued). "Similar to GSDME, GSDMB is cleaved by granzyme A to unleash its pore-forming activity, resulting in the killing of GSDMB-positive cancer cells through pyroptosis." (PMID 37134086, 2023). "In different cancers, GSDME has different expression levels and functions, and even the subcellular localization of GSDMD affects cancer progression and immune response." (PMID 37415742, 2023). "Chemotherapy-induced and GSDME-dependent pyroptosis of macrophages may not only contribute to the depletion of tissue-resident macrophages and impairment of innate immunity, but it may also engender a systemic inflammatory milieu that weakens the chemotherapeutic effects on cancers." (PMID 38104141, 2023). "This study thus highlights the critical role of GSDME-mediated pyroptosis in oncolytic ORFV-based antitumor immunity and identifies combinatorial cancer therapy strategies." (PMID 36641456, 2023). "Gasdermin E (GSDME) is a membrane pore-forming molecule that has been shown to execute pyroptotic cell death and thus to serve as a potential cancer checkpoint." (PMID 36604548, 2023). "By analyzing more than 30 different types of human cancer cell lines in the CCLE database, we found that GSDME was expressed at low levels in AML cell lines." (PMID 37679782, 2023). "In this study, the effects of DAP3, GSDME, PLK1, and PPP2R5B knockdown on cancer cell growth were analyzed by DepMap, a cancer survival-dependent gene database." (PMID 37415742, 2023). "In this work, COF-919-mediated photodynamic and photothermal combination therapy elicits GPX4-related ferroptosis and gasdermin E (GSDME)-dependent pyroptosis, inducing an acute inflammatory response and boosting cancer immunotherapy." (PMID 37660063, 2023). "Depmap database was used to explore genome-wide knockout library screening data, and pan-cancer analysis of DAP3, PPP2R5B, PLK1, and GSDME genes on cancer cell growth." (PMID 37415742, 2023). "The effects of GSDME and Gasdermin A3 (GSDMA3) on suppressing cancer proliferation by promoting cytotoxic responses of lymphocytes are reported." (PMID 37071001, 2023). "Significantly upregulated PRGs included PYCARD in 12 cancers; GSDMB in 10 cancers; IL18 in 9 cancers; GSDMD, CASP8, GZMB, and GPX4 in 8 cancers; AIM2 and CASP6 in 7 cancers; GZMA in 6 cancers; GSDME, CASP4 and DHX9 in 5 cancers; GSDMA and GSDMC in 4 cancers." (PMID 36605187, 2022). "Six GSDM family genes (i.e., GSDMA, GSDMB, GSDMC, GSDMD, GSDME, and PJVK) have long been described in other fields; however, they have been rarely investigated in a pan-cancer setting." (PMID 36003332, 2022). "For the next step, we investigated whether caspase-3/GSDME was involved in GW-8510 induced pyroptosis since caspase-3 activation followed by clipping of GSDME within the N terminus plays a major part in switching apoptotic cell death to pyroptotic cell death in various cancers." (PMID 35756622, 2022). "Conclusively, CME causes caspase‐3‐dependent apoptosis and pyroptosis in A549 through caspase‐3/PARP and caspase‐3/GSDME pathways, and it provides basic insight into clinic application of CME for cancer patients." (PMID 35035907, 2022). "The GSDM family includes six members, GSDMA, GSDMB, GSDMC, GSDMD, GSDME (DFNA5), and PJVK (Pejvakin, DFNB59), which can induce pyroptosis, thereby regulating the tumorigenesis of various cancers." (PMID 36505798, 2022). "The expression of selected 6 PRGs (GSDMC, GSDMD, GSDME, NLRP3, NLRC4, and IL1B) was assessed in 6 types of cancers and adjacent normal tissues." (PMID 36605187, 2022). "This pyroptosis was achieved by inhibiting the expression of c-myc and mitochondrial hexokinase II (HK-II) in cancer cells, leading to the activation of the BAD/BAX-caspase-3 cascade, and then cleaves GSDME." (PMID 36091247, 2022). "In 2017, new research showed that GSDME can convert caspase-3-mediated apoptosis induced by TNF or chemotherapy drugs to pyroptosis, providing new insights into cancer chemotherapy." (PMID 36189207, 2022).